GAPDHP65 (glyceraldehyde 3 phosphate dehydrogenase pseudogene 65)
Synonyms: formerly GAPDL10; GAPDHL10
Gene: Processed pseudogene on chromosome X (46,439,709 to 46,440,714, reverse strand). Ensembl gene ENSG00000235587.
Diseases named in the same sentence as GAPDHP65 in open-access papers:
GAPDHP65 is named in the same sentence as 1 disease in open-access papers, as found by Europe PMC text mining. Sharing a sentence is not in itself a finding about the gene and the disease. The quoted sentences say what the papers report.
tumor (1 paper, 2022). "The ncRNA GAPDHP65 (Glyceraldehyde 3 Phosphate Dehydrogenase Pseudogene 65) is related to the already known GAPDH regulation of glycolysis and has a pivotal role in tumor metabolism, which also explains why GAPDH represents an attractive target for therapeutic intervention." (PMID 35456196, 2022).